HIF1A (hypoxia inducible factor 1 subunit alpha)
Diseases named in the same sentence as HIF1A in open-access papers (continued):
Sharing a sentence is not in itself a finding about the gene and the disease.
cancer (continued). "However, expression of HIF-1α, and VEGF is merely regulated by metformin therefore metformin is less influence to cancer metastatic proteins." (PMID 28915611, 2017). "It has been reported that hypoxia could induce the expression of HIF-1α and subsequently activated CD73-A2AR adenosine pathway, which benefited to the immune escape of cancer cells." (PMID 28592285, 2017). "This was corroborated also with a further accumulation of HIF-1α, an effect not observed in other cancer cell lines taken into the study." (PMID 29100402, 2017). "Several reports have indicated the coexpression of HIF‐1α and ETS‐1 in cancer." (PMID 28236660, 2017). "After an analysis of the HIF-1α/HIF-1β dimerization inhibitor, we proceeded to test whether ACF affects HIF-1α and HIF-1α -related pathways in cancer cells." (PMID 29097800, 2017). "In addition, both of HIF-1α and VEGF are involved in angiogenesis, which is an important feature of cancer metastasis for cellular behavior." (PMID 28915611, 2017). "We also examined HIF-1α expression when MiaPaCa2 cells were exposed to PX-478, noscapine, and phenethyl isothiocyanate, as these compounds were known to inhibit HIF-1α expression in different cancer cells." (PMID 29152137, 2017). "However, the expression of HIF-1α and major histocompatibility complex class I -related chain A/B (MICA/B) are negatively correlated in cancer tissues." (PMID 29263932, 2017). "Of the four PHDs known so far, PHD2 appears to be the main HIF-1α regulator and key oxygen sensor, which implies PHD2 may have a regulatory role in the pathogenesis of cancer." (PMID 28038470, 2017). "On the one hand, HIF-1a exerts some of its effects through miRNAs, most notably miR-210 in various cancer and noncancer cell types." (PMID 29069829, 2017). "Inhibition of PHD2, but not PHD1 or PHD3 by siRNA is sufficient to upregulate HIF-1α under normoxic conditions, which has been observed in various cancer and primary cell types." (PMID 29163780, 2017). "As compared to other cancer types, in ccRCC, the differential activation of target genes leads to contrasting effects on cancer progression, as high HIF-2α expression enhances tumorigenic activity, whereas high HIF-1α has tumour suppressive effect." (PMID 28680592, 2017). "Furthermore, isoflavones sensitize cancer cells to radiotherapy through altered activation of APE1/Ref-1, NF-κB, and HIF-1α." (PMID 28423366, 2017). "Additionally, it is well known that LPA leads to enhanced HIF‐1α expression followed by activation of its downstream targets, such as VEGF, which promotes cancer progression." (PMID 28236660, 2017). "The hypoxic environment in 3D versus 2D culture were assessed by western blotting or immunofluorescence for HIF1α, and the effect of hypoxia on VEGF-A gene expression in 3D cultured cancer cells was assessed by western blotting with the use of the HIF1α inhibitor, 2-methoxyestradiol (2-MeOE2)." (PMID 29200966, 2017). "Consistent with previous studies, we found that hif-2α, rather than hif-1α, showed a chronic response pattern, which was more compatible with the observed chronic metabolic changes of cancer cells in continuous hypoxia." (PMID 28705232, 2017). "Thus in cancer cells an autoregulatory loop exits, in which NF-κB and HIF-1α upregulate the expression of TG2, while TG2 further enhances the NF-κB and HIF-1α-driven transcription including its own transcription resulting in the maintenance of high TG2 levels." (PMID 28840829, 2017). "Here we identify MIR31HG as a hypoxia-inducible lncRNA and therefore we name it LncHIFCAR (long noncoding HIF-1α co-activating RNA); we describe its oncogenic role as a HIF-1α co-activator that regulates the HIF-1 transcriptional network, crucial for cancer development." (PMID 28639619, 2017). "However, Propofol decreased HIF-1α accumulation induced by hypoxia or even isoflurane-induced HIF-1α activation, and partially reduced cancer cell malignant activities." (PMID 27028996, 2016).
cancer (continued). "Further studies are needed to understand the regulatory effect of UBXD7 on HIF1α’s stability and functions in the presence and the absence of hypoxia in cancer cells." (PMID 27754413, 2016). "It has been well established that the induction of HIF1α expression and its subsequent dimerization with HIF1β to function as a transcription factor in hypoxic conditions is involved in EMT and migration of many different cancer cell types." (PMID 27166196, 2016). "Our findings suggest that combinational therapies that target mTOR/HIF-1α/SK1 may overcome docetaxel resistance and have a clinical benefit in human cancers." (PMID 27821815, 2016). "Intriguingly, recent advances in cancer research have revealed that hypoxia-induced HIF2α, but not HIF1α, promotes hypoxic cell proliferation by enhancing the expression of Oct4 and the transcriptional activity of c-Myc." (PMID 27270657, 2016). "We selected four mRNAs that are well studied in cancer: PIM1, HIF1A, TNFα, and c-MYC34." (PMID 26926077, 2016). "HIF-1α is a subunit of HIF, which plays an important role in cancer progression." (PMID 27325313, 2016). "As the hypoxic response and regulation of iron metabolism are tightly interconnected, HIF1A may be involved in regulating genes that maintain iron homeostasis, e.g., transferrin, TFR1, ceruloplasmin, and heme oxygenase 1 in cancer." (PMID 26560875, 2016). "To complement these data, we investigated the effects of docetaxel on the expression of HIF-1α target genes (Glut1, CA9, LDHA, and BNIP3) involved in the metabolism of cancer cells and pro-apoptotic genes (CASP3, CASP8, and CASP10) in siJNK2-transfected MDA-MB-231 cells under hypoxic conditions." (PMID 27263528, 2016). "Although genetic alterations of various genes have been shown to affect HIF-1α expression, genetic mutations of HIF-1α in cancer have not been well studied." (PMID 26757928, 2016). "In addition, HIF1α activates OCT4 and Notch facilitating stem cell renewal, contributing to the immortalization and increasing survival of cancer stem cells." (PMID 26798421, 2016). "Some HIF-1α upstream regulatory molecules such as NOTCH, mTOR (mechanistic target of rapamycin) and LKB1 can also regulate LOX expression indirectly through HIF-1α and mediates cancer progression." (PMID 28036074, 2016). "Furthermore, we have shown that induction of melanogenesis is related to a significant up-regulation of HIF-1α and HIF-1-dependent pathways, pathways that are recognized as the contributory to the increased aggressiveness of cancer in general." (PMID 26910282, 2016). "This microRNA-HIF-1α interaction loop provides new insights in the regulation of HIF-1α-dependent transcriptional activities and its downstream biological effects, including cancer cell metabolism." (PMID 26934324, 2016). "Using specific pharmacological inhibitors and siRNAs to investigate the potential role of individual MAPKs in docetaxel-induced PHD1 activation in hypoxic cancer cells, we found that the JNK inhibitor SP600125 reduced PHD1 phosphorylation and restored HIF-1α accumulation." (PMID 27263528, 2016). "AE treatment significantly restored epithelial cell marker protein E-cadherin, inhibited the stromal cell marker protein vimentin, and suppressed EMT-associated transcription factors, including Twist, Snail, Slug, and HIF-1α, inhibiting EMT induction in cancer cells." (PMID 27391337, 2016). "The HIF-1α and EMT have an important role in the development of VM, and in the case of cancer." (PMID 27806701, 2016). "In cancer cells, however, HIF-1α protein levels are generally increased, independent of the oxygen level, thus stimulating HIF-1α/HIF-1β transactivation and regulation of HIF-1 target genes." (PMID 27602585, 2016). "In addition, previous studies have shown that HIF1α can induce the EMT and expression of Slug in many cancer cells." (PMID 27166196, 2016).
cancer (continued). "Indeed, we observed that the miR-592 knockdown-mediated upregulation of the WSB1 level increased the expression of HIF-1α, which plays an important role in critical aspects of HCC cancer biology, especially glucose metabolism." (PMID 27153552, 2016). "In order to decipher the molecular mechanism of HIF-1α and p65/RelA regulation by PKM2 in cancer cells cultivated in hypoxic atmosphere or normoxia we involved various biochemical assays such as Western blotting, immunoprecipitation, reporter gene assay and ELISA." (PMID 26739387, 2016). "Considering the compelling evidence regarding IL-1β-mediated regulation of HIF-1α, a key regulator of PFKP and the glycolysis pathway in cancer cells, we further dissected if the IL-1β-HIF-1α signaling cascade is involved in ABCB5-mediated regulation of glycolysis." (PMID 27560924, 2016). "Indeed, MLN4924, an indirect inhibitor of CRLs, induces autophagy in multiple cancer cell lines resulting from inactivating mTORC1 by the accumulation of DEPTOR and HIF1α." (PMID 27293474, 2016). "Myc and HIF1A are the best-known transcriptional regulators controlling expression of glycolysis genes, such as GLUT1, HK2, PDK1, and LDHA, whose expression levels are highly elevated in cancer cells." (PMID 26989077, 2016). "Also, hypoxia and HIF-1α have been shown to induce epithelial-to-mesenchymal-transition (EMT), increasing the metastatic potential of carcinomas." (PMID 27634881, 2016). "On the contrary, lack of association between HIF-1α/VEGF and the basal-like phenotype or triple negative subtype in our study agrees well with previous findings in human carcinomas." (PMID 26760782, 2016). "We provide evidence in this study that intermittent induction of HIF1α(PP) in vitro produced lasting effects on malignant progression of different cancer cell lines, unexpectedly independent of continued expression of the transgene." (PMID 25893706, 2015). "The possible explanation for this phenomenon is that HIF-1α enhances the expression of matrix metalloproteinases (MMPs) which can degrade most of the components of the extracellular matrix (ECM) and facilitate the invasion and metastasis of cancer cells." (PMID 25811359, 2015). "However, few studies have been reported concerning the correlation between HIF-1α and the SHH pathway in human cancers." (PMID 25811359, 2015). "Both HIF-1α and Stat3 promote aerobic glycolysis and downregulate oxidative phosphorylation in cancer cells, suggesting that GRIM-19 may downregulate aerobic glycolysis by reducing HIF-1α and Stat3 levels and activities." (PMID 25575809, 2015). "Consistent with this, we observed HIF1α-dependent reduction of ACC1 levels, which could limit the initial step in FAs biosynthesis, supporting the idea that cancer cells scavenge lipids from the extracellular environment." (PMID 25605240, 2015). "This suggested that the EGFR signaling pathway acts as an upstream regulator for HIF-1α and that targeting EGFR may be beneficial for cancer treatment by affecting HIF-1α expression and translocation." (PMID 25997612, 2015). "Hence, due to the similar abilities of HIF-1α and ZEB1 to induce EMT and the overlapping phenotypes of HIF-1α and ZEB1 in null mice, it is likely that these two genes are located in the same pathway to regulate cancer metastasis." (PMID 26057751, 2015). "Hypoxia and HIF-1α are also key to maintenance of cancer cell stemness via Notch1 signaling, and hypoxia induces expression of genes associated with stemness in ovarian cancer." (PMID 26343197, 2015). "LDH-5 is composed of four LDH-A units which is overexpressed in many cancers including PDAC as a result of post-translational or transcriptional c-Myc, K-Ras, HIF-1α, and FOXM1 (forkhead box protein M1) dependent regulation, and is associated with poor prognosis." (PMID 26164081, 2015). "Additionally, HIF-1α directly controls the expression of LDHA; HIF-1α and LDH5 are commonly expressed at high levels in cancer cells." (PMID 25635878, 2015).
cancer (continued). "All these studies suggest complex roles for HIF-1α and HIF-2α in cancer." (PMID 25893706, 2015). "We observed that HIF-1α and SCF have higher expression in cancer samples." (PMID 25799412, 2015). "Signal transducers and activators of transcription 3 (STAT3) is the main transcription factor through which IL-6 signals in target cells, where it regulates many genes including those that promote cancer proliferation and metastasis (e.g., TGF-β1) and angiogenesis (e.g., HIF-1α)." (PMID 26016502, 2015). "The absence of the PKM2/HIF-1α/DEC1 complex does not allow PC3 cancer cells to downregulate miR205 expression once treated with CAFs CM." (PMID 26183399, 2015). "Therefore, here we explored a new molecular mechanism for HIF-1α contributing to EMT and cancer metastasis through binding to ZEB1." (PMID 26057751, 2015). "The most prescient findings of the present study are that miR-622 directly targets HIF-1α as assessed with three algorithms and that the resultant repression of HIF-1α inhibits cancer cell migration and invasion as assessed in vitro in two lung tumor cell lines under hypoxia." (PMID 26528854, 2015). "In addition to Hif1a, the Wnt/β-catenin pathway signalling also controls EMT upon hypoxic stress in cancer." (PMID 26161955, 2015). "The study also suggests that HIF-1α can promote malignant progression at its own expense, which might account for HIF-1α inactivation in human cancer." (PMID 25893706, 2015). "Hypoxia is a potent inducer of HIF1α, but it did not appear to be necessary for KLF5 loss to induce HIF1α, at least in cancer cell lines, because the morphological and molecular alterations in PC-3 and DU 145 cells were detected under normoxic conditions." (PMID 25896712, 2015). "It is likely that this occurred because these cancers had not yet progressed to the point where they had become pro-oxidative with higher PGC-1α/HIF-1α levels, increased OxPhos and greater ROS production." (PMID 25688484, 2015). "Both HIF-1α and canonical Wnt signaling have been reported to induce the EMT in cancer cells." (PMID 25396735, 2014). "Activation of Slug by HIF-1α increased the expression of membrane-type 4 matrix metalloproteinase (MT4-MMP, also known as MMP-17) in human cancer cells, which promotes in vitro invasiveness of the cells and in vivo colonization and growth of the cells in the lungs, via an EMT-independent mechanism." (PMID 25937967, 2014). "Data suggest that NO may facilitate intracellular autocrine crosstalk between Tβ4 expression and HIF-1α induction indicating Tβ4 could be a novel target controlled by HIF-1α, potentially increasing cancer cell migration." (PMID 25271630, 2014). "Even though HIF-1α has been found upregulated in several cancers, probably because of the intratumoral hypoxia, its involvement in cancer initiation and progression is not clear." (PMID 25593996, 2014). "Collectively, different lines of evidence argue that targeting of HIF-1α may disrupt IMQ-induced HIF-1α up-regulation and activity, counteract the IMQ-enhanced aerobic glycolysis and enhance the IMQ-induced apoptosis in cancer cells." (PMID 24658058, 2014). "However, HIF-1α and HIF-2α knockdown produced opposite effects on canonical Wnt signaling and on the expression of cancer stem cell and differentiation markers." (PMID 25396735, 2014). "Importantly, hypoxia, through the transcription factor hypoxia inducible factor 1 alpha (HIF-1α), is the major regulator of cancer cell metabolism, stimulating the Warburg effect." (PMID 25296855, 2014). "For example, the SNP 1772 C > T of HIF-1α gene was detected in several cancers but it was absent for colorectal, and cervical cancers." (PMID 25302049, 2014). "In terms of interactions of miRNA and HIF-1α, more reports refer to its interactions in cancer rather than in chondrocytes, which are exposed to hypoxia in the physiological environment and in which the necessary roles of HIF-1α on hypoxia are taken." (PMID 24790587, 2014).
cancer (continued). "In addition, TNF-α, interferon-gamma (IFN-γ), early growth response gene-1 (EGR-1), hypoxia-inducible factor 1 alpha (HIF-1α), and transforming growth factor-beta (TGF-β) upregulate flTF in cancer cells and endothelial cells." (PMID 25084809, 2014). "Taken together, we hypothesized that induction of HIF-1α promotes the switch to aerobic glycolysis to maintain the intracellular ATP level, thereby gaining the survival advantage in IMQ-treated cancer cells." (PMID 24658058, 2014). "We used PC-3 cancer cells with low levels of AKT and HIF-1α expression to test whether nobiletin affects VEGF expression." (PMID 25342300, 2014). "Because the IGF-1R/Akt pathway is a common upstream regulator of p70S6K, HIF-1α, and COX-2, we hypothesized that glucosamine inhibits cancer cell proliferation through this pathway." (PMID 24438088, 2014). "Since AKT activation stimulates aerobic glycolysis in cancer cells and facilitates higher energy consumption 48, in the absence of HIF-1α, it is likely that elevated levels of pAKT and pp70S6K promote greater energy consumption under hypoxic conditions." (PMID 24515947, 2014). "Moreover, silencing HIF-1α by siRNA significantly decreased OATP mRNA expression and blocked NIR dye uptake in cancer cells." (PMID 25361418, 2014). "After checking quartile distribution and cancer-related deaths, cut-off points correspondent to 75 percentile (value = 1.74) and median (value = 1.22) values were chosen to consider the overexpression of VEGF-A and HIF-1α, respectively." (PMID 26316946, 2014). "Interestingly, bimodal effects of 17-AAG in the same cancer cells had been observed that low-dose treatment (5-30 nM) with 17-AAG increased and high-dose treatment (1-3 μM) reduced hypoxic HIF-1α protein and activity, respectively." (PMID 24658058, 2014). "Volm and Koomagi showed that patients with HIF1α-positive carcinomas had significantly longer median survival time than patients with HIF1α-negative carcinomas." (PMID 24567056, 2014). "Moreover, the percentage of HIF-1α expression was significantly higher in the BRCA1-2 carriers (median value 15%, range 0–70) than in BRCAX cancers (median value 3%, range 0–64) (p<0.05), and in the sporadic group (median value 0%, range 0–60) (p = 0.0002)." (PMID 23326384, 2013). "Our data supported an additional function of HIF-1α in controlling stem cell plasticity and reprogramming the non-stem cancer cells population into stem-like cells." (PMID 24305593, 2013). "Possibly, HIF-2α, like HIF-1α, is predominantly regulated through hypoxia-dependent protein stabilization and genetic alterations, and under both normoxia and hypoxia, HIF-2α mRNA is also expressed constitutively in many cell types, including cancer cells." (PMID 24288553, 2013). "Although Gravdal and co-workers had demonstrated that castration-resistant cancers have increased HIF1α expression, to our knowledge no previous studies have looked at the correlation between normoxic expression of HIF1α and development of CRPC." (PMID 23342109, 2013). "VEGF, HIF-1α expression and MVD in BRCA1-2, BRCAX and Sporadic cancers." (PMID 23326384, 2013). "In a large cohort of colorectal cancers, HIF-1α but not HIF-2α was shown to have an important negative prognostic role in cancer aggressiveness and overall survival of patients." (PMID 23945296, 2013). "Expression analysis has revealed that a number of genes which regulate cancer invasion, such as CXCR4, pyruvate dehydrogenase kinase 1 matrix metalloproteinase 2, urokinase plasminogen activator receptor and fibronectin 1 are regulated by HIF-1α." (PMID 23740575, 2013).